KCNJ16 (potassium inwardly rectifying channel subfamily J member 16)
Description:
Inward rectifier potassium channels are characterized by a greater tendency to allow potassium to flow into the cell rather than out of it. Their voltage dependence is regulated by the concentration of extracellular potassium; as external potassium is raised, the voltage range of the channel opening shifts to more positive voltages. The inward rectification is mainly due to the blockage of outward current by internal magnesium. KCNJ16 may be involved in the regulation of fluid and pH balance. In the kidney, together with KCNJ10, mediates basolateral K(+) recycling in distal tubules; this process is critical for Na(+) reabsorption at the tubules.
Synonyms: Kir5.1; BIR9; HKTD
Tractability: Small molecule: it belongs to a druggable protein family. Antibody: UniProt places it where antibodies can reach, with high confidence; its Gene Ontology location is reachable by antibodies, with high confidence; UniProt predicts a signal peptide or a membrane-spanning region.
Gene: Protein-coding gene on chromosome 17 (70,053,429 to 70,135,608, forward strand). Ensembl gene ENSG00000153822.
Subcellular location: Membrane; Basolateral cell membrane
Subcellular location (Human Protein Atlas): Vesicles
Pathways (Reactome):
Neuronal System: Activation of G protein gated Potassium channels; Inhibition of voltage gated Ca2+ channels via Gbeta/gamma subunits; Potassium transport channels
Gene Ontology:
Molecular function: inward rectifier potassium channel activity
Biological process: potassium ion transmembrane transport; potassium ion import across plasma membrane; potassium ion transport
Cellular component: basolateral plasma membrane; membrane; plasma membrane; voltage-gated potassium channel complex
Genetic constraint (gnomAD): Loss-of-function variants: 20 observed, 25.12 expected, observed/expected ratio (o/e) 0.8, 90% interval 0.56 to 1.16. The upper end of that interval is the gene's LOEUF score, 1.16, which puts it in group 5 of 6, group 1 being the genes least tolerant of losing a copy. Missense variants: 523 observed, 554.19 expected, observed/expected ratio (o/e) 0.94, 90% interval 0.88 to 1.01. Synonymous variants: 174 observed, 196.98 expected, observed/expected ratio (o/e) 0.88, 90% interval 0.78 to 1.
Homologues: Orthologues: chimpanzee KCNJ16 (99% identical), macaque KCNJ16 (99% identical), dog KCNJ16 (96% identical), rabbit KCNJ16 (96% identical), guinea pig KCNJ16 (94% identical), pig KCNJ16 (94% identical), rat Kcnj16 (93% identical), mouse Kcnj16 (92% identical), tropical clawed frog kcnj16 (63% identical), zebrafish kcnj16a (38% identical). Paralogues in human: KCNJ2 (42% identical), KCNJ12 (40% identical), KCNJ18 (40% identical), KCNJ4 (39% identical), KCNJ14 (38% identical), KCNJ3 (35% identical), KCNJ8 (34% identical), KCNJ9 (34% identical), KCNJ6 (33% identical), KCNJ11 (33% identical), KCNJ5 (32% identical), KCNJ1 (32% identical), and 3 more.